CXCR5 (C-X-C motif chemokine receptor 5)
Diseases named in the same sentence as CXCR5 in open-access papers (continued):
Sharing a sentence is not in itself a finding about the gene and the disease.
infection (continued). "The study showed that during early phase chronic infection, both CXCR5+ and CXCR5- CD8+ T were found in the blood, but at later stages on infection (day 30 onwards), only the CXCR5−CD8+ T cells were found in the blood." (PMID 37122741, 2023). "The absolute cell count of CXCR5+TIM-3+ and TIM-3+ cells of CD4+ and CD8+ T-cell compartments significantly increased from day 30 to 60, and remained high at least until day 90 of infection." (PMID 37691941, 2023). "We demonstrate that prior infection significantly increases the magnitude of the SARS-CoV-2-specific memory B cell response, its expression of the germinal center homing receptor CXCR5 and class switching following vaccination." (PMID 37573434, 2023). "Flow cytometry analysis of Tex subpopulations at day 90 of infection further confirmed the predominance of TIM-3+ cells within both CD4+ and CD8+ T-cell compartments in the lesion sites, compared to their respective CXCR5+ and CXCR5+TIM-3+ cells." (PMID 37691941, 2023). "At day 14 p.i., we sorted CD45.1+CD45.2+CD44+Tigit+IL-7Rα–PD-1+CXCR5+ and CD45.1+CD44+Tigit–IL-7Rα+PD-1+CXCR5+ CD4+ T cells and co-transferred them into CD45.2+ recipient mice followed by PR8 infection." (PMID 37330549, 2023). "These infection-induced ELAs were defined by the presence of ER-TR7+ fibroblastic reticular cells, CD21/35+ follicular dendritic cells (FDCs), CXCR5+ PD1+ T follicular helper-like phenotype, GL7+ CD95+ GC-like B cells, and plasmablasts/plasma cells." (PMID 37983289, 2023). "Further, we identified PD-1+ Tex subsets within both CD4+ and CD8+ T-cell compartments based on CXCR5 and TIM-3 expressions in lymph nodes and infection sites." (PMID 37691941, 2023). "On the other hand, the frequencies of CXCR5+TIM-3+ cells within both CD4+ and CD8+ T cells reached comparable values at 30 (2-4%) and 60 (7-10%) days after infection." (PMID 37691941, 2023). "Using flow cytometry, we identified Tex cells subtypes based on PD-1, CXCR5 and TIM-3 expressions in draining lymph nodes (dLNs) and lesion sites of C57BL/6 mice infected with L. mexicana at 30-, 60- and 90-days post-infection." (PMID 37691941, 2023). "In contrast, the expression levels of CD186, CXCR5, CCR9, CCR10 and CD103 were unaffected by the infection." (PMID 36298634, 2022). "It is somewhat unlikely that the infection of the CAR T cells by SIV and subsequent cell death is a major contributor to low persistence of our CD4-MBL CAR/CXCR5 T cells." (PMID 36582226, 2022). "CXCR5+CD8 T cells have attracted significant interest within multiple areas of immunology, cancer, and infection." (PMID 36314014, 2022). "On day 8 post LCMV-Armstrong infection, Mettl3fl/flCd4-Cre mice-derived CD4+ T cells had much lower cell numbers of CD44+CXCR5+ TFH cells than those of competitor bone marrow-derived CD4+ T cells." (PMID 33637761, 2021). "However, in HIV-1 controllers, CXCR5+CXCR3+PD-1low CD4+ T cells were associated with increased HIV-1 neutralizing antibody breadth and in acute HIV infection, frequencies of CXCR3+ Tfh1 cells correlated positively with p24 plasma IgG titers at 1 year post infection." (PMID 33996678, 2021). "Recently, IL-27 has been identified to play an intrinsic role in promoting the survival of CXCR5+ CD8+ T cells, which were important for maintaining the antiviral T cell response during LCMV Cl 13 infection." (PMID 34696381, 2021). "In response to the high viral titer infection, both CCL4 and CXCR5 were upregulated more robustly in young subjects compared to old subjects." (PMID 33796130, 2021). "We also identify a number of host proteins that are upregulated by HIV during infection, including CCR7, CXCR5, and CD69." (PMID 32452381, 2020). "Using flow cytometry, we measured GC B cell numbers and the expression of CXCR5, PD-1, IFN-γ, IL-21, T-bet, and Bcl6 in Teff for the first 30 days of infection." (PMID 32634740, 2020).
infection (continued). "On day 8 after infection with the LCMV Armstrong strain, Ezh2fl/flCd4-Cre mice exhibited a remarkable reduction in the virus-specific GP66–77 tetramer-positive CXCR5+ICOS+ TFH cell population in the spleen compared to that in Ezh2fl/fl control mice." (PMID 30842630, 2020). "Compared to CD8+CXCR5- T cells, CD8+CXCR5+ T cells produce different levels of interferon (IFN)-γ and tumor necrosis factor (TNF)-α during infection with lymphocytic choriomeningitis virus (LCMV) or HIV, and in chronic infections." (PMID 31663864, 2019). "In an acute infection model, ICOS is required for the early CXCR5+Bcl6+ TFH differentiation of antigen-specific T cells as early as 3 days following infection with lymphocytic choriomeningitis virus (LCMV)." (PMID 30405612, 2018). "In a chronic LCMV-Cl13 infection model, overexpressing Id2 or ablating TCF-1 leads to the impaired generation of virus-specific CXCR5+CD8 T cells and accordingly to increased viral loads." (PMID 29872434, 2018). "Studies using Il21−/− and Il21r−/− mice show that the in vivo generation of CXCR5+PD-1+ TFH cells in these mice is as robust as in wt mice following NP-KLH or NP-CGG immunization, or infection with LCMV or Influenza." (PMID 30405612, 2018). "The similarities and differences of CXCR5+CD8 T cells in lymphocytic choromeningitis virus (LCMV)-CI13 and human immunodeficiency virus (HIV)/simian immunodeficiency virus (SIV) infection." (PMID 29872434, 2018). "In LCMV-Cl13 infection, compared to CXCR5−CD8 T cells, virus-specific CXCR5+CD8 T cells exhibit elevated effector cytokine expression, including IFN-γ and TNF-α, in response to antigen stimulation." (PMID 29872434, 2018). "Quite different expression kinetics were observed for CXCR5, CCR5, and CCR7, which were elevated on the highest number of cells early during infection and decreased by 14, 30, and 60 days post infection." (PMID 27207308, 2016). "Following Lm‐2W1S infection, three subsets of CD4+ T cells can be defined: CXCR5−PD‐1−T‐bet+ effector cells (Teff) that give rise to Tem cells, CXCR5+PD‐1−Bcl‐6+ central memory precursors that give rise to Tcm cells and CXCR5+PD‐1+Bcl‐6+ Tfh cells." (PMID 25754933, 2015). "The expression of the Tfh classical markers CxCR5 and PD-1 in lymph node CD4 T cells increased progressively after infection at the transcript and protein levels, though without statistical value." (PMID 24763747, 2014). "Further studies in Cxcr5−/− mice showed an elevation in bacterial burden in the GT and increased numbers of neutrophils, activated DCs and activated NKT cells early after infection." (PMID 23189125, 2012). "When measuring mRNA expression levels from BAL cells, chemokines CCL2, CCL5, CCL8, and CXCL10 and receptors CCR5 and CXCR5 were significantly upregulated only in JBNU-22-N01 infection at 7 dpi compared with the negative control." (PMID 40459260, 2025). "Meanwhile, Tigit-negative Tfh-like cells upregulate CD127 expression by day 14 post-infection (after GC formation) and give rise to CXCR5+ TM cells with or without CCR7 expression." (PMID 40391228, 2025). "Our longitudinal analysis of lymph nodes revealed that the CXCR5+ subpopulation augmented as infection progressed, whereas both CXCR5+TIM-3+ and TIM-3+ subsets increased progressively during the first 60 days, and thereafter decreased during the remaining 90 days post-infection." (PMID 37691941, 2023). "CXCR5+ T cell expansion was proportional to the time elapsed between diagnosis and delivery, in asymptomatic, but not in symptomatic, infections." (PMID 37490342, 2023). "These antigen-specific CXCR5+ CD8+ T cells exhibit memory-like properties and are co-expressed with antigen-specific T cell factor 1 (TCF1+) CD8+ T cells in the germinal center during lymphocytic choriomeningitis virus (LCMV) Cl13 infection." (PMID 36452930, 2022).
infection (continued). "To investigate mechanisms involved in establishing both central and effector memory, we analysed Ag-specific TM cells soon after they had formed, 7 days after infection with Lm-2W1S, and separated 2W1S-specific CD4 T cells into CXCR5-ve Tem and CXCR5+ve Tcm cells." (PMID 34108962, 2021). "As expected, the CD8 T‐cell pool specific for FLU, an acute infection, does not contain CXCR5+PD‐1+ CD8 T cells." (PMID 33098668, 2021). "In contrast, various populations of class-switched MBCs expressing low levels of or no CXCR5 and CCR6, including T-bet+ atypical MBCs, were associated with reduced risk of infection." (PMID 34128836, 2021). "The higher frequencies of Tfh in infected relative to PRE cells suggest that after infection, HIV may increase co-expression of PD1 and CXCR5, the markers we had used to define Tfh." (PMID 33910003, 2021). "This highlights CSF CXCR5+CD4 T cells a key target and potential missing link to the poorly understood phenomenon of intrathecal B cell and antibody responses with relevance for infection control, chronic inflammation and CNS autoimmunity." (PMID 34446066, 2021). "Evaluation of infection-induced changes in CD4 T-cell differentiation at Day 7 revealed a strong phenotypic shift to Th1 effectors (CXCR3+), Th1 polarized Tfh cells (CXCR3+ CXCR5+) and Th1 Th17 (CXCR3+ CCR6+) CD4 T cells as demonstrated by tSNE plots constructed using flow data." (PMID 33483492, 2021). "Our data and the results from the study by Leong and colleagues are from experiments that assessed the cytotoxicity of CXCR5+CD8+ T cells relatively early, at days 7-8 post-immunisation/infection, while He and colleagues performed these analyses on cells obtained 21 days post-infection." (PMID 34326833, 2021). "There was donor variation in the infection efficiency within the Tfh population (CXCR5hiPD-1hi), however evaluation of MFI of each marker individually showed that latent infected cells had higher CXCR5 MFI compared to productive and uninfected (p < 0.05)." (PMID 34531866, 2021). "On the other hand, most circulating CD4+CD45RO+CXCR5+ cells did not express PD-1, indicating that cTfh cells were in a resting status, irrespective of the infection and clinical condition." (PMID 32296649, 2020). "CXCR5 expression on NK cells was also low in SLT of CM compared with AGM in chronic SIV infection, correlating with previous data on the higher levels CXCR5 + NK cells in SLT during chronic SIVagm infection as compared with chronic SIVmac infection." (PMID 33013901, 2020). "Evaluation of infection-induced changes in CD4 T cell differentiation at Day 7 revealed a strong phenotypic shift to Th1 effectors (CXCR3+), Th1 polarized Tfh cells (CXCR3 + CXCR5+) and Th1 Th17 (CXCR3 + CCR6+) CD4 T cells." (PMID 32818217, 2020). "This was not the case after infection as a prominent population of donor WT CD4+ T cells co-expressed CXCR5 and PD-1, suggesting a possible Tfh cell fate." (PMID 32348365, 2020). "The IFN-γ-expressing T effector cells generated following P. chabaudi were predominantly positive for CXCR5, a marker for TFH cells, and acquired the ability to express IL-21 and IFN-γ, later in the course of infection and in the memory phase of the immune response." (PMID 31867283, 2019). "Additionally, and as observed 2 weeks after infection, differences in CD4+CXCR5+PD1+ T cells were detected, comparing the different mouse strains, regarding both basal levels and the ones determined in 8-week-infected animals." (PMID 30881923, 2019). "In chronic LCMV-Cl13 infection, we have shown a greater therapeutic potential for LCMV-specific CXCR5+CD8 T cells than the CXCR5− subset upon adoptive transfer to chronically infected mice, as well as synergistic effects that reduce the viral load when combined with anti-PD-L1 treatment." (PMID 29872434, 2018).
infection (continued). "Unfortunately, little is known about these recently described follicular CD8+ T cells, and whether the contrasting results are due to the presence of distinct CXCR5+CD8+ T cell subsets, differences in the infection models studied or other yet unknown factors." (PMID 29725327, 2018). "The levels of these CXCR5+CD8+ T cells in LN were higher in HIV-infected individuals compared to healthy donors, and they were detected in close proximity to viral RNA+ cells, probably starting from primary infection on." (PMID 29725327, 2018). "To assess the contribution of NKT and TfH cells to the pool of IL-4-producing cells at different times of infection, we gated on TCRβ+ IL-4-GFP+ lymph node cells and analyzed the proportion of this population that was CD1d-tetamer+ (NKT cells) or CXCR5+ (TfH cells)." (PMID 29249358, 2018). "In the present study, the early accumulation of prions within the MLN of CXCR5ΔDC mice was not impaired, suggesting that the prions had established infection within the MLN independently of CXCR5-expressing conventional DC." (PMID 28275192, 2017). "The accumulation of TFH (CD4+ PD1+ CXCR5+) and GC B (CD19+ Fas+ GL7+) cells was decreased in old mice relative to adult mice at days 4 and 6, although nearly equivalent levels of TFH and GC B cells were present at 8 days post infection." (PMID 26204259, 2015). "Therefore, we conclude that CXCR5 expression by the TH2 priming cDC2 subset supports upregulation of Chi3l1, and Chi3l1 can, in turn, function as a DC-derived secretory factor to support protective TH2 responses following infection." (PMID 41012147, 2025). "However, this modulation only minimally altered Tcf-1+ and GzmB+ subsets, nor did it enhance CXCR5 expression within the Tcf-1+ subset, contrasting the patterns observed in s.c. infection routes." (PMID 40169810, 2025). "Separation of the CXCR5-expressing migratory DCs from the T cell zone of the lymph nodes appears important for the function of these cells as deletion of Cxcr5 in DCs impairs development of IL-4+ CD4 T cell responses during both Hp and Trichuris muris infections." (PMID 41012147, 2025). "Thus, CXCR5+CD8+ T cells as well as Tfh cells could play an important part in the regulation of cellular and humoral immunity during the acute phase of infection and post-COVID." (PMID 36146713, 2022). "Increasing expression of ICOS and CXCR5 on CD4+ T cells has also been reported, and circulating Tfh numbers increase for the duration of infection, thus, the increase in ICOS and CXCR5 may be attributed to the enhanced differentiation of Tfh, and increased glycolysis." (PMID 35493515, 2022). "In contrast, IgD+IgMlow classical MBCs and two populations of atypical MBCs (IgM+IgD+ and class‐switched T‐bet+ cells) expressing low or no CXCR5 and CCR6, along with CD127+CD25low TH2‐like memory CD4+ T cells, were associated with reduced odds of symptomatic infection." (PMID 35475529, 2022). "Thus, to specifically investigate a role for CXCR5+CD8+ T cells in mediating IgG2c class switching in response to IAV, we transferred WT or Cxcr5-/- OT-I cells into B6.Ifng-/- mice, infected the recipients with x31-OVA and harvested the mLNs on day 6 post-infection for flow cytometric analyses." (PMID 34326833, 2021). "The role of the SNPs TLR2 + 2477 G > A and CXCR5 + 10950 T > C in the severity of infection could not be confirmed in this study." (PMID 33430411, 2021). "As noted, Ahmed initially found that stem-like PD-1loCD8+ Tex express CXCR5; however, these cells co-express high amounts of Ccr7 transcripts, migrate in response to a CCL19/21 gradient in vitro, and localize to the splenic T cell zone in vivo after Clone 13 infection." (PMID 34354714, 2021). "However, the regulation of the CXCR5+IL-21+IFN-γ+ subset was independent of Bcl6 during infection of P. chabaudi in the mouse." (PMID 31867283, 2019).
infection (continued). "Despite this, our studies using CXCR5 KO mice indicate that this signaling axis is either not critical or functionally redundant with respect to the host response to C. rodentium 10 days post-infection." (PMID 30973939, 2019). "To fully understand the nature and function of CXCR5+PD-1+CD8+ T cells, we might need to compare scRNA-Seq data of these T cells derived from different experimental situations, such as chronic LCMV and other infections." (PMID 31562329, 2019). "A subset of CXCR5+ THF cells that also express programmed death-1 (PD-1) have been shown to facilitate the development of a strong B-cell response in early HIV infection, and preservation of peripheral CXCR5+ TFH cells correlate with long-term control of infection." (PMID 31354634, 2019). "Although the expression of PD-1 and CXCR5 significantly increased amongst both NK1.1 positive and negative CD4+ T cells between days 5 and 8 p.i., NK1.1+CD4+ T cells more frequently expressed PD-1 and CXCR5 relative to NK1.1−CD4+ T cells throughout the first two weeks of infection." (PMID 30374346, 2018). "Interestingly, the frequencies of CXCR5 expressing precursor (CD19+CD27+IgMhiCD21loCD1c+CD10+) and mature MZ-like (CD19+CD27+IgMhiCD21hiCD1c+CD10-) populations remained unaltered during the course of infection in all HIV-1-infected individuals." (PMID 27203285, 2016). "Furthermore, B cell-deficient μMT mice infected with LCMV were shown to have no defect in CD4+ T cell expression of Bcl6 or CXCR5 at day 3 post-infection, suggesting that B cells are not exclusively responsible for promoting early Tfh cell induction." (PMID 27559335, 2016). "However, by week 3 post-infection, there was a substantial reduction in CD4+ T cells expressing these Tfh cell markers in Icos−/− mice, and the remaining Tfh cells were unable to form PD-1++CXCR5++ GC Tfh cells." (PMID 27559335, 2016). "Intriguingly, we found that direct TGF-β promoted the differentiation of Tfh precursor cells at day 3 post infection (p.i.), such that there were about 1/3 fewer CD25lo CXCR5+ Tfh precursor cells in the absence of direct TGF-β signals (WT = 60.25% ± 4, KO = 42% ± 3.3)." (PMID 25569154, 2015). "It is however worth referring that confocal imaging revealed the presence of some CxCR5+ PD1+ CD4 T cells inside B cell areas, at early time points after infection, suggesting that some bona fide Tfh cells might engage into the GC pathway, even though their numbers appear compromised." (PMID 24763747, 2014). "Importantly, we also found that in vitro infection of CXCR5-expressing CD4 T cells did not impact CXCR5 surface expression." (PMID 24497824, 2014). "Following Lm-2W infection, three subsets of 2W1S-specific CD4+ T cells have been elegantly described 19: CXCR5−PD-1−T-bet+ effector T cells (where PD-1 is programmed death-1), CXCR5+PD-1−Bcl-6+ cells that give rise to central memory cells and CXCR5+PD-1+Bcl-6+ TFH cells." (PMID 24771127, 2014). "Specific inhibitors of Akt would decrease productive infection, by favoring cell death during virus attachment to CD4+ CCR5+ target cells, and reduce immune activation to prevent Fas-dependent death of uninfected CXCR5+ PD-1+ CD4 T cells including T follicular helper cells that share this phenotype." (PMID 23742646, 2013). "Thus, in contrast to IL-4-secreting CXCR5+ Tfh cells, not only are Th2 effector cell responses efficiently generated in ICOS−/− mice, it appears that ICOS is in fact involved in suppressing Th2 cell effector responses at the infection site." (PMID 23319295, 2013). "We evaluated UGT (uterine horns+oviducts) pathology in mice treated with anti-CXCL13 Ab and Cxcr5−/− mice by examining inflammatory scores in the UGT from hematoxylin and eosin stained slides and fibrosis from trichrome stained slides of oviducts after infection." (PMID 23189125, 2012).